TSC2 (TSC complex subunit 2)
Diseases named in the same sentence as TSC2 in open-access papers (continued):
Sharing a sentence is not in itself a finding about the gene and the disease.
tumor (continued). "Anti-PD-1 therapy enhanced T cells infiltration in TSC2-deficient tumors, inhibited tumor growth by 62% (p < 0.0001) and improved the survival rates of LAM mice (p < 0.0001)." (PMID 39614360, 2024). "Meanwhile the study of Liu found that anti-PD-1 blockade after sequential rapamycin therapy slowed the growth rates of tumor cells in TSC2-deficient tumors." (PMID 39614360, 2024). "TSC is an autosomal dominant genetic disorder, and in 60% of cases, it is due to spontaneous mutation in TSC1 and TSC2 tumor suppressor genes." (PMID 39130912, 2024). "Two bi-steric mTORC1 inhibitors (RMC-4627 and RMC-6272) were assessed on multiple tumor cell lines with mTORC1 hyperactivation secondary to TSC1 or TSC2 loss." (PMID 37909334, 2023). "We found altered expression of 42 tumour‐associated proteins in TSC2‐ cells relative to TSC2+ cells." (PMID 37337371, 2023). "The plasma EV signature will be reflective of the whole body, so in the case of TSC patients, these EVs will be derived from both TSC tumours (mTORC1‐active) and cells with a single TSC2 mutation (normal mTORC1 levels)." (PMID 37337371, 2023). "Tumor cells from control or B7-H3 knockdown Tsc2-deficient 105K tumors were isolated using the MACS Tumor Cell Isolation Kit and the transcriptomic profiles of these cells was analyzed by RNA-sequencing." (PMID 36869048, 2023). "TSC manifestations are caused by mutations in either TSC1 (on chromosome 9q34) or the TSC2 gene (on chromosome 16p13.3), both recognized as tumor suppressors." (PMID 36769603, 2023). "We found that reduced B7-H3 inhibition upregulates MHC-II expression in Tsc2-deficient tumor cells in vivo, where high IFN-γ producing T cells are present in the tumor milieu." (PMID 36869048, 2023). "We focussed on endoglin, enolase γ, VEGF, IL‐6 and CCL20 which were all enriched in TSC2‐ EVs, compared to TSC2+ EVs, due to known associations with tumour‐promoting functions." (PMID 37337371, 2023). "In in vitro and xenograft models, palbociclib+lapatinib shows higher anti-tumor activity than monotherapy and overcomes the resistance of the TSC2 c.4349 C > G-related variant to anti-HER2 therapy." (PMID 37160904, 2023). "From a genetic point of view, these isolated SEGAs are thought to result from two purely somatic mutations in one of the TSC genes (TSC1 or TSC2) limited to the tumor." (PMID 36769603, 2023). "Tuberous sclerosis complex (TSC) is a rare genetic multisystem disorder caused by loss-of-function mutations in the tumour suppressors TSC1/TSC2, both of which are negative regulators of the mammalian target of rapamycin (mTOR) kinase." (PMID 37108467, 2023). "In preclinical models, we also revealed that Glrx knockdown reduced lung colonization of TSC2‐deficient cells and suppressed tumour growth, supporting that Glrx was a critical regulator of the survival of TSC2‐deficient cells in vivo." (PMID 37478294, 2023). "Some of the proteins with elevated expression in TSC2‐ cells have previously been linked to mTORC1‐driven tumours in TSC, including HIF‐1α, MMPs, VE‐cadherin, IL‐6 and VEGF." (PMID 37337371, 2023). "We characterised EVs secreted from TSC2‐deficient and TSC2‐expressing cells and identified a distinct protein cargo in TSC2‐deficient EVs, containing an enrichment of proteins thought to be involved in tumour‐supporting signalling pathways." (PMID 37337371, 2023). "We show EVs from TSC2‐deficient cells promote cell viability, proliferation and growth factor secretion from recipient fibroblasts within the tumour microenvironment." (PMID 37337371, 2023). "B7-H3 downregulation results in markedly decreased tumor growth in mouse models with loss of TSC2 and mTORC1 hyperactivation." (PMID 36869048, 2023).
tumor (continued). "We profiled the protein cargo by expression analysis of 84 tumour‐associated proteins in TSC2+ and TSC2‐ cells and their cell‐derived EVs using the Proteome Profiler Human XL Oncology Array (R&D Systems)." (PMID 37337371, 2023). "For example, TSC2 (tuberous sclerosis complex 2) was a tumor suppression gene that was reported that specific mutations of this gene led to the development of renal and extra-renal tumors in mice." (PMID 37582720, 2023). "Whole-exome tumor sequencing in this patient revealed a somatic nonsense mutation (Q1178*) in the tumor-suppressor gene TSC2 that inactivates the gene, allowing for activation of the mTOR pathway." (PMID 36855200, 2023). "We co-cultured these cells with Tsc2-deficient 105K tumor cells and employed an imaging-based time-lapse cytolytic assay, assessing cell death with Cytotox Green." (PMID 36869048, 2023). "TSC2-depleted tumor cells were shown to be susceptible to both the pSTAT1 inhibitor (fludarabine) and the pSTAT3 inhibitor (cryptotanshinone)." (PMID 36231025, 2022). "TSC is associated with a high sporadic mutation rate, resulting from inactivating variants in TSC1 (OMIM: 191100) and TSC2 (OMIM: 613254) tumor suppressor genes." (PMID 35692821, 2022). "Despite a similar growth in vitro (not shown), when the cells were implanted subcutaneously to NSG mice, tumor development was faster for control MM1.S than TSC2 and NPRL2 KO variants." (PMID 36400754, 2022). "Previous genetic studies have shown that renal AML occurring in TSC cases was caused by the inactivation of both pairs of alleles of either TSC1 or TSC2, which is consistent with Knudson’s 2-hit tumor suppressor gene model." (PMID 35145067, 2022). "Collectively, TSC2 loss is associated with the tumor mutational burden (TMB) and facilitated T cell activation in NSCLC." (PMID 35119931, 2022). "Beyond the four groups defined above, patients P1, P4, P6, P7, and P16 were also associated with the loss of the TSC2 gene, which plays the role of a tumor suppressor." (PMID 35887000, 2022). "Collectively, TSC1/TSC2 loss defines a distinct subtype of NSCLC characterized as inflamed tumor microenvironment and superior sensitivity to ICB." (PMID 35119931, 2022). "Overactivation and dysregulation of the mTOR pathway, which are caused by TSC1 or TSC2 abnormalities, promote tumor formation." (PMID 35359647, 2022). "The specific mechanisms by which pyrotinib targets TSC2-deficient tumor cells were investigated in this study, as well as the interaction between EGFR and CD24." (PMID 36231025, 2022). "Tumors in TSC have been suggested to be caused by the inactivation of both alleles of either TSC1 or TSC2 genes, consistent with Knudson’s two-hit tumor suppressor gene model." (PMID 35145067, 2022). "Pyrotinib specifically targeted TSC2-deficient cells, inhibited tumor cell viability and induced apoptosis through EGFR-STAT3/CD24 Loop in vivo and in vitro." (PMID 36231025, 2022). "Through these transcription factors, Ref-1 promotes angiogenesis, inflammation, and a metabolic transformation that further supports the tumor growth of TSC2-deficient cells." (PMID 36551683, 2022). "Tuberous Sclerosis Complex (TSC) is an autosomal dominant genetic syndrome caused by mutations in either the TSC1 or TSC2 tumor suppressors." (PMID 35883484, 2022). "The data reveal that Ref-1 redox-mediated signaling is a driver of cell migration, invasion, and tumor growth in TSC2-deficient cells." (PMID 36551683, 2022). "TSC1/TSC2 loss defines a distinct subtype of NSCLC with inflamed tumor microenvironment and superior sensitivity to ICB therapy." (PMID 35119931, 2022). "eFT226 significantly blocked tumor growth with limited drug toxicity in nude mice bearing Tsc2-deficient MEFs and the HCC cells PLC/PRF/5." (PMID 35805935, 2022).
tumor (continued). "Mice harboring TSC2-deficient 105K xenograft tumors treated with vehicle control (DMSO) showed progressive tumor growth." (PMID 36220392, 2022). "Tuberous sclerosis complex (TSC) is an inherited genetic disorder characterized by mutations in TSC1 or TSC2 class of tumor suppressers which impact several organs including the kidney." (PMID 35814396, 2022). "We show that blocking AGTR1 in TSC2-deficient cells results in cell death in vitro and inhibition of tumor growth in vivo." (PMID 36220392, 2022). "Mice were randomly divided into pyrotinib-administered and control groups after subcutaneous tumor-bearing using TSC2-deficient MEF cells." (PMID 36231025, 2022). "Loss of function mutations in TSC1 and TSC2 genes results in constitutive mTOR activation and tumor progression." (PMID 35250965, 2021). "Rapamycin has been shown to increase miR-29b, which promotes mTORC1-hyperactive growth in TSC2-deficient cells via downregulation of the TS retinoic acid receptor β, or reduction in miRNAs, such as miR-29b itself, to increase tumor suppressor pathways." (PMID 33668092, 2021). "The TSC1/TSC2 complex is the main upstream regulator of mTOR, and hyperactivated mTOR, caused by the loss of TSC1 or TSC2, leads to uncontrolled cell proliferation and tumor growth." (PMID 34341336, 2021). "G3BP1 inhibition also prolongs tumor-free survival and represses tumor growth in a subcutaneous in vivo model derived from a TSC2-deficient renal tumor." (PMID 34778262, 2021). "Actually, TSC2 encodes a tumor suppressor, which is capable of stimulating specific GTPases and negatively regulate mTOR signaling." (PMID 34249677, 2021). "We observed overexpression of GD3 in LAM, wherein mutations in TSC1 or TSC2 are responsible for tumor development." (PMID 34806651, 2021). "Intriguingly, T1 and T3 of HCC10 showed distinct branches for these two tumor regions possessed different mutational loci in TSC2, even though they shared a common ancestor in mutations including AXIN1, STK11 and TERT." (PMID 34211467, 2021). "TSC is caused by mutations in two genes: TSC1 (hamartin gene, 9q34) and TSC2 (tuberin gene, 16p13.3) that act as tumor suppressors inhibiting the mammalian target of rapamycin (mTOR)." (PMID 33669772, 2021). "Twenty-five of 31 patients had tumor mutation profiling: 8 of 9 (89%) patients with a TSC2 mutation achieved a confirmed response versus 2 of 16 (13%) without TSC2 mutation (P < .001)." (PMID 34637337, 2021). "As to renal lesions, patients carrying TSC2 mutations usually have larger initial tumor size, higher risk for a growing RAML, and higher risk for hemorrhage." (PMID 31927531, 2020). "To determine the in vivo efficacy of rapamycin on tumor growth, we first generated xenograft tumors of Tsc2-deficient Eker Rat uterine leiomyoma-derived luciferase-tagged cells." (PMID 32807195, 2020). "This disorder is caused by loss of function mutations in the tumour-suppressor genes TSC1 or TSC2, encoding the proteins hamartin and tuberin." (PMID 33178126, 2020). "Alterations in cellular energy metabolism are a hallmark of cancer, and metabolic reprogramming is particularly critical for the survival of Tsc2-deficient tumor cells." (PMID 32078667, 2020). "Previous studies showed that while the involvement of rapamycin in TSC2 patients control tumour growth, its efficacy in managing neuropsychiatric-associated behaviour in TSC2 patients has remained unclear." (PMID 33076974, 2020). "Their effects in LAM have been revealed in in vivo and in vitro studies in which chloroquine inhibited TSC2-deficient cell survival and reduced xenograft tumor size to 60%." (PMID 33072782, 2020). "In the hamartoma syndrome, tuberous sclerosis complex (TSC), loss of function of TSC1 or TSC2 leads to mTORC1 hyperactivation and the formation of cysts and tumours in multiple organs." (PMID 35582282, 2019).
tumor (continued). "The original tumour cells were found to contain an inactivating mutation in TSC2, explaining the acute sensitivity of the tumour to mTORC1 inhibition." (PMID 35582282, 2019). "It is caused by mutations in either the TSC1 or TSC2 gene, which result in upregulation of the mammalian target of rapamycin (mTOR) pathway and subsequent tumor growth in various organs such as the brain, heart, skin, eyes, kidney, lung, and liver." (PMID 31039793, 2019). "In the developmental disorder tuberous sclerosis complex (TSC), patients carry mutations in either TSC1 or TSC2, leading to an increase in mTORC1 signaling and tumor formation throughout the body." (PMID 30910807, 2019). "Tuberous sclerosis complex (TSC) is a rare autosomal dominant genetic disorder associated with mutations in TSC1 and TSC2 genes, upregulation of mammalian target of rapamycin signaling, and subsequent tumor formation in various organs." (PMID 31039793, 2019). "Several studies have shown that either anti-PD-1 or anti-PD-L1 antibodies reduce TSC2-deficient tumor growth in vivo and enhance mouse survival." (PMID 31878201, 2019). "TSC is an autosomal dominant condition caused by mutations in either TSC1 or TSC2 and is characterized by mTORC1 hyperactivity, tumor growth in multiple organs, neurocognitive problems and epilepsy." (PMID 30308940, 2018). "The decreased levels of eIF2αP delay tumor formation of TSC2-deficient cells in immune deficient mice, an effect that is significantly alleviated in mice subjected to an anti-oxidant diet." (PMID 29449538, 2018). "These finds provide a potentially important link between the pro-oxidant function of eIF2αP and inhibition of TSC2-deficient tumor formation in mice." (PMID 29449538, 2018). "We also found that decreased eIF2αP elicits pro-oxidant and pro-death effects in TSC2-deficient cells and is associated with an inhibition of tumor initiation in immune deficient mice." (PMID 29449538, 2018). "This new clinically viable drug combination causes a significant level of cell death in TSC2-deficient tumor spheroids." (PMID 30308940, 2018). "We further assessed the role of eIF2αP in tumor formation of TSC2-deficient cells in mice based on previous work showing that the TSC2-deficient MEFs employed in our study are tumorigenic in immunocompromised mice." (PMID 29449538, 2018). "TSC is also an autosomal dominant genetic syndrome and is caused by germline mutations in either the TSC1 or TSC2 tumor suppressor genes, which encode the Tsc1 and Tsc2 proteins, also known as hamartin and tuberin." (PMID 29774133, 2018). "Collectively, the data suggested that a significant fraction (~50%) of the anti-tumor effects of eIF2αP on TSC2-deficient cells in mice is alleviated by the anti-oxidant diet." (PMID 29449538, 2018). "Sirolimus, a highly specific inhibitor of mTORC1, can suppress the growth of spontaneously occurring renal tumours in a Tsc2+/− Eker rat model and in Tsc1+/− and Tsc2+/− mice, as well as in TSC2-deficient xenograft tumours in immune-deficient mice." (PMID 30428897, 2018). "Our work shows that eIF2αP is a nodal point of mTORC1 signaling, which can determine the susceptibility of TSC2-deficient cells to oxidative insults and their efficacy in tumor formation in mice maintained on anti-oxidant diet." (PMID 29449538, 2018). "Our findings reveal a previously unidentified connection between mTORC1 and eIF2αP in TSC2-deficient cells with potential implications in tumor suppression in response to oxidative insults." (PMID 29449538, 2018). "Somatic mutations in TSC1 and TSC2 also contribute to tumor growth via unopposed mTOR signaling, and sporadic AML is similarly characterized by somatic loss-of-function alterations in TSC2." (PMID 30285856, 2018). "We attempted to sequence the normal kidney and tumor tissue to identify possible somatic mutations in TSC1 or TSC2; however, unfortunately we were unable to obtain high quality sequence information." (PMID 29774133, 2018).
tumor (continued). "Limited molecular studies have demonstrated recurring copy number alterations and TSC1 or TSC2 mutations in the sporadic tumours." (PMID 30123932, 2018). "The PI3K/mTOR pathway was again implicated when analysing the expression profiles of PanNETs, with a particularly evident association between low PTEN and TSC2 expression levels and development of metastasis, tumour progression and poor overall survival." (PMID 29321190, 2018). "By contrast, IT tumours were enriched in mutations affecting the PI3K/mTOR pathway (TSC2, PTEN), while in the MLP subtype, both chromatin remodeling and PI3K/mTOR were affected." (PMID 29321190, 2018). "Our study addresses the cell-autonomous effects of eIF2αP on TSC2-deficient tumor formation in immune deficient mice." (PMID 29449538, 2018). "TSC1/TSC2 mutation analysis was performed as part of routine clinical care on blood or tumor DNA for 19 subjects, such that 7 had TSC1 and 12 had TSC2 mutations." (PMID 29221145, 2017). "We also identified two low-frequency somatic TSC2 mutations in tumour tissues: a frameshift mutation in 18-RA1 and nonsense mutation in 06-RA1." (PMID 28643795, 2017). "Tumors of adult mice showed increased Tsc2- allele, providing evidence of an expansion of KO cells in tumor-containing tissues." (PMID 28695825, 2017). "TSC is thought to result from loss of function of hamartin or tuberin (encoded by TSC1 and TSC2, respectively), two tumor suppressors, normally acting in a complex to inactivate mammalian target of rapamycin complex 1 (mTORC1)." (PMID 28275008, 2017). "Loss-of-function mutations in either the TSC1 or TSC2 gene lead to activation of mTORC1, which is believed to be responsible for the tumor development in TSC." (PMID 28903387, 2017). "Compared to the expected recombination in the limbs, low levels of Tsc2- allele were present in kidney, liver and spleen of Tsc2cKOPrrx1-cre neonates, indicating the presence of KO cells before tumor formation." (PMID 28695825, 2017). "TSC2 mutation caused a consecutive activation of mTORC1, which led to suppression of Akt activity and restricted malignant transformation of benign tumor cells." (PMID 28591720, 2017). "Mutations in PIK3CA (25.9%), INPP5B (30.8%), SRC (99%) and TSC2 (46.7%) were observed in Tumor #3, and Tumor #4 harbored an NF1 gene mutation (43.5%)." (PMID 27057633, 2016). "Despite the relative benign nature of these tumors, emerging evidence indicates that TSC2-deficient cells exhibit characteristics of low-grade neoplasia, including invasion of extracellular matrix and metastasis to distant organs." (PMID 27458154, 2016). "This disorder is caused by inactivating mutations in either of two tumor suppressor genes: TSC1 or TSC2." (PMID 27078846, 2016). "TSC1 and TSC2 are the tumor-suppressor genes mutated in tumor syndrome TSC (tuberous sclerosis complex)." (PMID 27409169, 2016). "Tuberous sclerosis complex (TSC), caused by loss-of-function mutations in the TSC1 or TSC2 gene, is characterized by benign tumor formation in multiple organs." (PMID 27078846, 2016). "Tuberous Sclerosis Complex (TSC) is a multi-system genetic disease caused by autosomal dominant mutations in the tumor suppressor genes encoding hamartin (TSC1) or tuberin (TSC2)." (PMID 26892894, 2016). "The tumor angiogenesis and growth in murine xenografts were held after infusion of TSC2 deficient monocytes or reduced with monocytes overexpressing TSC2." (PMID 28074082, 2016). "In most patients with TSC, a mutation in either TSC1 or TSC2 results in an aberrant activation of mTORC1, causing benign tumor growth." (PMID 25574245, 2015). "Patients with TSC1, TSC2 or LKB1 (STK11) tumour mutations will be eligible for treatment with AZD2014." (PMID 26410619, 2015). "In the genetic disease TSC, which is caused by mutations in Tsc1 or Tsc2, patients develop benign tumours in multiple organs including the brain." (PMID 25210733, 2014).